BRCA1 (BRCA1 DNA repair associated)
Diseases named in the same sentence as BRCA1 in open-access papers (continued):
Sharing a sentence is not in itself a finding about the gene and the disease.
breast cancer (continued). "HIFs are involved in the pathogenesis and progression of many cancer types, including triple-negative breast and BRCA1-associated breast cancer, as they provide a growth advantage to rapidly growing tumours where angiogenesis may not be adequate." (PMID 36831687, 2023). "A Phase III trial (OlympiA) showed the usefulness of postoperative addition of olaparib, a PARP inhibitor, in patients with germline BRCA1/2 pathogenic variant-positive breast cancer with a high risk of recurrence who completed neoadjuvant/adjuvant chemotherapy." (PMID 37804479, 2023). "The same group completed a similar phase II trial investigating the effects of anti-progestin ulipristal acetate (5 mg daily) on surrogate markers of breast cancer risk in high-risk premenopausal women (BRCA1/2 mutation carriers or high lifetime risk by assessment models; NCT02408770)." (PMID 37583424, 2023). "In BRCA1-deficient breast cancers, cisplatin also acts concomitantly with STING activation." (PMID 38139802, 2023). "Furthermore, possibly due to limiting angiogenesis, hypoxia-induced HIF-1α overexpression has been reported to be more than 2-fold more frequent in BRCA1-mutation-associated breast cancer than in sporadic breast cancers." (PMID 36831687, 2023). "Under this scenario, it may seem counter-productive to inhibit RNF126, as BRCA1 deficiency is one of the notable markers in breast cancer." (PMID 37760968, 2023). "In addition, 20 of the 69 patients who had a prior history of breast cancer had a relapse, leading to death in two patients (BRCA1- and BRCA2-mutated)." (PMID 36831483, 2023). "When the BRCA1 gene mutates or loses its function, it will lead to abnormal biological processes such as DNA damage repair and cell cycle, thereby increasing the risk of the occurrence and development of breast cancer." (PMID 37759912, 2023). "PARP inhibitors inactivate the PARP family of enzymes and are approved for use in the treatment of metastatic germline BRCA1 or BRCA2-mutated breast cancers and in the adjuvant setting for high-risk, HER2-negative germline BRCA1 or BRCA2-mutated early breast cancer." (PMID 37173991, 2023). "Furthermore, a more advanced stage at diagnosis and the presence of multiple foci of breast cancers are more common in patients with BRCA1 and BRCA2 mutations than in patients with sporadic tumors." (PMID 35778884, 2023). "The homologous recombination (HR) repair pathway for DNA damage, particularly the BRCA1 and BRCA2 genes, has become a target for cancer therapy, with poly ADP-ribose polymerase (PARP) inhibitors showing significant outcomes in treating germline BRCA1/2 (gBRCA1/2) mutated breast cancer." (PMID 38098088, 2023). "A recent report has shown that altered BRCA1 expression in peripheral T cells could result in aberrant transcription related to antitumor immunity, which may contribute to the elevated breast cancer risk among BRCA1-mutation-carrying women." (PMID 37240365, 2023). "Thus, BRCA1/2-related breast cancers represent another example in which the mutational burden and T cell responses are not linked." (PMID 37444415, 2023). "Therefore, we used a PDX model BR‐05‐0028, generated from a BRCA1‐deficient human breast cancer, to further evaluate the effect of thioparib." (PMID 36652375, 2023). "Patients who could have a higher hereditary risk of developing breast cancer or who might benefit from particular treatments or preventive measures might be identified by genetic testing, such as finding BRCA1 and BRCA2 mutations." (PMID 38192969, 2023).
breast cancer (continued). "PVs and LPVs in BRCA1/2 genes are correlated to a high risk of developing breast cancer and/or ovarian cancer (Hereditary Breast and Ovarian Cancer syndrome, HBOC); additionally, in recent years, an increasing number of BRCA 1/2 variants have been identified and associated with pancreatic cancer." (PMID 37046793, 2023). "However, breast cancer can occur in younger females due to certain risk factors, such as the inheritance of mutated BRCA1 or BRCA2 genes or the use of contraceptives." (PMID 38143654, 2023). "However, studies conducted in 2005 showed that breast cancer cells with mutations in the BRCA1 or BRCA2 genes are more susceptible to PARP-inhibition." (PMID 37509303, 2023). "HCC1937, a TNBC line derived from a 24-year-old woman with a family history of breast cancer and a germline mutation in BRCA1, was sensitive to pilocarpine, RITA, TG101348, and tremorine, and resistant to AS703026, dasatinib, midostaurin, nilotinib, PD0325901, PD198306, and PD98059." (PMID 37508580, 2023). "Constitutional BRCA1 mutations occur in 10% of breast cancer patients and 20% in younger women." (PMID 37662839, 2023). "Although an LOH test can recognize a subset of breast cancers with a BRCA1/2 mutation for potential PARPi treatment, comprehensive genomic profiling may be required to target a larger patient population." (PMID 37173992, 2023). "Most breast cancers with BRCA1 mutation carriers are triple negative, but only ~10–20% are ER." (PMID 36831644, 2023). "Furthermore, we did not evaluate other predictive factors, such as the effect of the type of surgery, family history of breast cancer, and the presence of a breast cancer gene 1/breast cancer gene 2 (BRCA1/BRCA2) gene mutation." (PMID 37182081, 2023). "As a consequence, considering the important roles of BRCA1 and BRCA2 mutations in development of breast cancer, strategies in supplying the wild type BRCA1 and BRCA2 gene could be promising as a therapeutic option." (PMID 36631481, 2023). "There is no definite study of BRCA1 in gliomas, but it has been reported that the mutation of the BRCA1 gene may be related to some types of brain tumors, such as metastatic brain tumors of breast cancer and ependymoma." (PMID 37759912, 2023). "Although the detection rate in this study is extremely high this bias in testing should mean a cautious approach to assessing the likelihood of a BRCA1 pathogenic variant in those with a sporadic metaplastic breast cancer aged >60 years as the detection rates are likely to be very much lower." (PMID 37592173, 2023). "Therefore, identifying genes associated with breast cancer susceptibility, such as BRCA1 and BRCA2, is important for improving surveillance and developing effective preventive interventions." (PMID 37138170, 2023). "Given that BRCA1/2-mutation also lead to increased and unresolved R-loop formation, targeting the R-loop modulating machinery may be beneficial in breast cancer." (PMID 37108225, 2023). "However, their mutations are associated with cancer, especially breast cancer, and the cancer risk varies with the mutation position in BRCA1 or BRCA2 genes." (PMID 36765522, 2023). "Detection of variants in BRCA1/2 genes is clinically important in breast cancer patients." (PMID 37656691, 2023). "Furthermore, the combined therapy of double immune checkpoint inhibitors (ICIs), such as anti-PD1 and anti-CTLA4, with chemotherapy provoked strong systemic and intratumoral immune responses in BRCA1-mutated breast cancer." (PMID 37813891, 2023). "Phase 3 OlympiA clinical trial for Olaparib has demonstrated that patients with germline BRCA1 or BRCA2 pathogenic or likely pathogenic variants could obtain a benefit in early breast cancer." (PMID 37365643, 2023). "At the same time, the frequency of BRCA1/2 mutations may be higher in patients with familial hereditary breast cancer—about 1–2% to 40%—depending on the population and region." (PMID 37628606, 2023).
breast cancer (continued). "If BRCA1-deficient breast cells are particularly sensitive to hormonal treatment, this could lead to a significantly higher risk of breast cancer compared with BRCA2 variant carriers associated with very early menopause and hormonal contraception use." (PMID 37340476, 2023). "However, prophylactic surgery is usually only recommended for women at the highest risk for breast cancer, for example, women with a pathogenic mutation in a breast cancer-associated gene (e.g., BRCA1)." (PMID 37881237, 2023). "The key protein is the breast cancer susceptibility gene BRCA (BRCA1/2)." (PMID 39872888, 2023). "The prevalence of P/LP BRCA1/2 gene mutations among the specific subgroup of triple negative (TN) disease was 33.9%, and it was 60% among patients with both TN disease and a family history of breast cancer as published by KHCC group." (PMID 37400873, 2023). "Moreover, breast cancer in young patients was strongly associated with family history and genetic mutations in the BRCA1 or BRCA2 genes leading to the development of breast and ovarian cancers." (PMID 37143985, 2023). "Although the inherited mutation in BRCA1 and -2 known tumour suppressor genes is a well-defined predictor of breast cancer, a strong correlation between the presence of SSTR subtypes and breast cancer might also predict some of the therapeutic approaches." (PMID 38203605, 2023). "In addition, we included PARP, where patients are selected for treatment with PARP inhibitors (PARPis) based on the assessment of mutation in the breast cancer genes 1 and 2 (BRCA1 and BRCA2)." (PMID 37195374, 2023). "Thus, we evaluated the association between vitamin D and/or calcium supplement use and breast cancer among women with a pathogenic variant (mutation) in BRCA1 or BRCA2." (PMID 37345127, 2023). "They observed a 32% risk reduction (OR 0.68; 95% CI 0.52–0.91; p = 0.008) in breast cancer for breastfeeding for at least one year among BRCA1 germline variant carriers and a more significant decrease in risk for two or more years of breastfeeding (OR 0.51; 95% CI 0.35–0.74)." (PMID 37628558, 2023). "However, IDC remains the most common type of breast cancer in those with mutations in the BRCA1 or BRCA2 genes." (PMID 37686673, 2023). "According to previous reports, 3.4% of Middle Eastern breast cancer cases carry BRCA1/2 mutation." (PMID 38017116, 2023). "Studies have demonstrated that an estimated 46% of women with a BRCA1 mutation born before 1920 developed breast cancer by the age of 70, with rates rising up to 59% for women born after 1950, with some carriers having risks above 90% at the 5th and 95th percentiles." (PMID 37623478, 2023). "The annual diagnosis of new breast cancer cases stands at 6000 cases in Kenya, which could hypothetically imply that the extent of BRCA1 and BRCA2 mutation is higher in our population and goes undetected due to lack of screening." (PMID 37719058, 2023). "In addition, BRCA1-deficient breast cancer, non–small cell lung cancer, and colitis mouse models suggest that STING activation can repolarize immunosuppressive M2-like macrophages to the immune-activating M1-like phenotype." (PMID 36976649, 2023). "In this review, we discuss surgical treatment options for patients with breast cancer known to have a high-penetrant cancer-predisposing gene, like the BRCA1 and BRCA2, and address the oncological safety of less aggressive surgical options, for both patients and unaffected carriers." (PMID 37781190, 2023). "Moreover, we did not perform germline sequencing for variants that predispose to breast cancer, like BRCA1 and BRCA2 pathogenic variants." (PMID 37599285, 2023). "However, after a 10-year follow-up period, they observed a significantly lower breast cancer risk among BRCA1 mutation carriers who used ET compared to EPT (12% vs 22%, p = 0.04)." (PMID 36765666, 2023).
breast cancer (continued). "High BMI and weight gain might therefore lead to higher estradiol levels due to increased aromatase activity and consecutively to postmenopausal BRCA1-associated breast cancer." (PMID 37340476, 2023). "A systematic literature review investigated whether physical activity levels during adolescence and young adulthood could decrease the lifetime risk of breast cancer among individuals carrying BRCA1 or BRCA2 germline variants." (PMID 37628558, 2023). "A large sequencing study on female breast cancer found that BRCA1 and BRCA2 mutations could account for 2% of the cases (subtracting the proportions in healthy individuals) and that all germline mutations accounted for 5.6% of the cases." (PMID 36882784, 2023). "Tumors that are phenotypically and genetically similar to familial BRCA1-associated breast cancer have similar properties to those and are defined as “BRCAness” (BRCA-like tumors) and these common properties may be important for treatment." (PMID 37628606, 2023). "Breast cancer was the first target of genetic risk scores with the discovery of BRCA1." (PMID 37328908, 2023). "Four PARPis (Olaparib, Rucaparib, Niraparib, and Talazoparib) are approved by the FDA for the treatment of advanced ovarian and breast cancers with BRCA1/2 deficiency, and three PARPis (Veliparib, Pamiparib, and Fluzoparib) are currently under clinical trials for evaluation." (PMID 37892162, 2023). "Interestingly, after menopause the percentage of ER-positive BRCA1-associated breast cancer increases." (PMID 37340476, 2023). "Aim of this study is to compare early post-operative outcomes and patient’s satisfaction after skin-sparing and/or nipple-sparing mastectomy (SSM/SNSM) followed either by breast reconstruction with one-stage prepectoral implantation or two-stage technique for breast cancer (BC) or BRCA1/2 mutation." (PMID 36401760, 2023). "Furthermore, we found that renal cell carcinomas (RCCs) in Brca1 mutants show more genomic alterations, including c-Myc amplification, which is indeed frequently observed in the breast carcinoma of human BRCA1 mutants and is a risk for poor prognosis." (PMID 36639692, 2023). "However, it was associated with increased survival following breast cancer when considering BRCA1 and BRCA2 carriers together and BRCA1 carriers alone." (PMID 36900415, 2023). "If verified, future therapeutic intervention studies targeting SULT1A1 in BRCA1 pathogenic variant carriers may lead to new medical options for reducing breast cancer risk." (PMID 36203093, 2022). "Indeed, PARPi-sensitive primary breast cancer cells exhibited elevated BRCA1 promoter methylation, which was associated with impaired BRCA1 expression." (PMID 36497275, 2022). "However, patients with breast cancer aged less than 40 years with the BRCA1 pathogenic variant in exons 1-10 in stage I who underwent RRBM + RRBSO had an almost similar impact on survival compared with those who underwent RRBM alone." (PMID 36580360, 2022). "Less frequent susceptibility genes, other than BRCA1/2, have been reported for breast cancer." (PMID 35191009, 2022). "Importantly, the frequency of BRCA pathogenic variant (PV) carriers among ER+/HER2- breast cancer patients has been underestimated, and 50% of all BRCA1/2 mutated breast cancers are actually of ER+/HER2- subtype." (PMID 35158866, 2022). "Moreover, the loss function of BRCA1 (a major breast cancer suppressor) impairs mitophagy leading to breast cancer metastasis." (PMID 35541900, 2022).
breast cancer (continued). "In addition to sporadic breast cancers, the expression of TRα and TRβ was confirmed in breast cancers associated with BRCA1 gene mutations." (PMID 35160139, 2022). "Asian patients may have breast cancer at a younger age than their Caucasian peers because their BRCA1/2 mutations are thought to have different contributions than those of Caucasians." (PMID 36140642, 2022). "Majority of inherited breast cancer is associated with BRCA1 and BRCA2." (PMID 36268285, 2022). "There have been very few genetic studies on pre-disposition to mammary tumours in cats, with the focus having been to look for the presence of germline mutations in BRCA1 and BRCA2, as the cumulative breast cancer risk in humans is 72% for BRCA1 and 69% for BRCA2 carriers." (PMID 36288160, 2022). "The PARP inhibitor olaparib is currently approved for the treatment of PCa patients harboring a somatic or germline Breast Cancer 1 or 2 (BRCA1/2) mutation, similarly, deficiency of several other DNA damage repair (DDR) proteins has been detected in (late stage) PCa patients." (PMID 35887398, 2022). "Importantly, BRCA1 mutation carriers have strongly expressed their preference for breast cancer risk reduction and desire a novel prevention drug that is currently not available." (PMID 35418083, 2022). "However, these variants are too rare in the general population to explain more than a small proportion of breast cancer cases, especially among Chinese women where the prevalence of BRCA1 and BRCA2 mutations is lower than that in women of European ancestry." (PMID 35395775, 2022). "Furthermore, the preclinical and experimental data support therapeutic inhibition of the RANK pathway for the primary prevention of BRCA1-associated breast cancer." (PMID 35418083, 2022). "This suggests that CIN determined by the LPWGS method may be used as a valuable prognosis factor in BRCA1-mutated breast cancer patients." (PMID 34403063, 2022). "Indeed, PARPi in combination with STING agonists demonstrated superior anti-tumor efficacy than PARPi combined with macrophage depletion via anti-CSF1R in our syngeneic GEMM of Brca1-deficient breast cancers." (PMID 35641483, 2022). "In one of the studies, it was observed that TNBC could also occur in women having a family history of BRCA1 mutated breast cancer." (PMID 35631368, 2022). "Our findings thus provide insights into the role of macrophages in PARPi therapy and demonstrate a mechanism underlying PARPi resistance that is mediated through bi-directional interactions between tumor cells and immune cells in BRCA1-deficient breast cancers." (PMID 35641483, 2022). "The datasets “Phenotypes” and “IlluminaHiSeq Gene Expression RNAseq” were downloaded in order to identify breast cancer patients with mutations affecting BRCA1 or BRCA2 or amplification affecting ErbB2 and the expression data of 20,530 different genes, respectively." (PMID 35740092, 2022). "We therefore aimed to identify synthetic lethal partners of EZH2 in BRCA1-deficient breast cancer." (PMID 35715861, 2022). "Telli and colleagues present a phase II clinical trial of the PARP inhibitor talazoparib in patients with solid tumors and show that the drug has activity in patients with breast cancer with mutations in other homologous recombination pathway genes beyond BRCA1 and BRCA2." (PMID 36253484, 2022). "BRCA1/2 or HRR mutation prevalence in HER2+ breast cancer remains poorly understood." (PMID 34979999, 2022). "The consequences of HMMR overexpression against a Brca1-mutant background expose the initial interplay of these alterations that may promote development of BRCA1-associated breast cancer." (PMID 35393420, 2022). "• miR-34a correlates directly with breast-cancer susceptibility genes BRCA1, and BRCA2." (PMID 37303494, 2022). "Their cumulative risk of breast cancer (BC) may be as high as 70% for carriers of both genes, whereas the risk of ovarian cancer (OC) is estimated to be 44% for BRCA1 carriers and 17% for BRCA2 carriers." (PMID 35123550, 2022).